POLD1 (DNA polymerase delta 1, catalytic subunit)
Diseases named in the same sentence as POLD1 in open-access papers (continued):
Sharing a sentence is not in itself a finding about the gene and the disease.
neutropenia (2 papers, 2017 to 2020). A decrease in the number of neutrophils found in the blood. "rs1726801, rs1673041 and rs3219341 in POLD1 showed significant association with neutropenia in patients receiving TP regimen." (PMID 28924235, 2017). "SNPs in POLD1 were significantly associated with overall survival and neutropenia." (PMID 32762026, 2020). "Polymorphisms in ERCC2, ERCC6, DDB2, RPA1, POLD1 and POLD3 presented significant association with neutropenia." (PMID 28924235, 2017). "In this study, POLD1 and POLD3 showed significant association with neutropenia." (PMID 28924235, 2017).
non-small cell lung carcinoma (2 papers, 2016 to 2023). A group of at least three distinct histological types of lung cancer, including non-small cell squamous cell carcinoma, adenocarcinoma, and large cell carcinoma.
pilomatricoma (2 papers, 2023 to 2025). "At the same time, clinically, patients with POL /POLD1 mutations are often accompanied by skin pigmentation, pilomatricoma and other skin lesions." (PMID 40019657, 2025).
thyroid cancer (2 papers, 2022 to 2023). "So far, POLD1 expression and its clinical significance have been investigated in colorectal, endometrial, renal, liver, breast, lung, and thyroid cancers." (PMID 36980791, 2023).
chronic myeloid leukemia (1 paper, 2025). "We speculate that hyperactive kinases, such as FLT3-ITD in AML cells or BCR-ABL in chronic myeloid leukemia cells and a subset of ALL cells, activate MYC and POLD1, and that this attenuates the cytotoxic effects of HDAC10 inhibition." (PMID 40301616, 2025).
clear cell renal cell carcinoma (1 paper, 2023). "However, the prognostic value of POLD1 and its relationship with tumor immunity in clear cell renal cell carcinoma (ccRCC) remains to be further explored." (PMID 37047824, 2023).
duodenal adenocarcinoma (1 paper, 2025). A carcinoma that arises from glandular epithelial cells of the duodenum. "Our report expands both the phenotypic and molecular spectrum of POLD1-associated PPAP by documenting the first duodenal adenocarcinomas in germline carriers and describing a novel variant." (PMID 41487566, 2025). "While duodenal adenomas have been associated with germline POLD1 variants in the past, this represents, to our knowledge, the first report of duodenal adenocarcinomas linked to constitutional POLD1 alterations." (PMID 41487566, 2025). "This study provides the first report of duodenal adenocarcinomas in POLD1 carriers, expanding the clinical spectrum of POLD1-related PPAP." (PMID 41487566, 2025). "However, additional tumor types were reported, most notably duodenal adenocarcinomas in both POLD1-positive families." (PMID 41487566, 2025).
duodenal cancer (1 paper, 2025). "When the likely pathogenic POLD1 variant was identified, his oncologist planned to discuss the potential benefits of immunotherapy at a multidisciplinary team meeting upon completion of the staging of his duodenal cancer." (PMID 41487566, 2025). "Until now, duodenal cancers had been described exclusively in POLE heterozygotes, a discrepancy that may partly reflect the smaller number of reported POLD1 families compared with POLE." (PMID 41487566, 2025).
gastritis (1 paper, 2025). Inflammation of the stomach. "In a marked contrast to the uninfected tissues, gastritis tissues infected with H. pylori exhibited weaker immunostaining of POLD1." (PMID 39924917, 2025). "Immunohistochemistry analysis showed elevated levels of ACVR1 in H. pylori-positive gastritis tissues, showing a negative correlation with POLD1 expression." (PMID 39924917, 2025). "The qRT-PCR analysis showed that the mRNA levels of ACVR1 was higher in H. pylori positive gastritis tissues, compared with H. pylori negative tissues, while POLD1 exhibited the opposite pattern." (PMID 39924917, 2025).
Hyperinsulinemia (1 paper, 2022). An increased concentration of insulin in the blood. "Fiorillo and coworkers found that an MDPL patient carrying the heterozygous single codon deletion c.1812-1814delCTC (p.Ser605del) in the POLD1 gene showed type 2 diabetes, hyperinsulinemia, and IR." (PMID 36354755, 2022).
hypertrophic cardiomyopathy (1 paper, 2023). A condition in which the myocardium is hypertrophied without an obvious cause. "In contrast, only three pathways, namely olfactory transduction, hypertrophic cardiomyopathy, and pantothenate and CoA biosynthesis, were activated when POLD1 exhibited a high expression in NAFLD." (PMID 37822923, 2023).
IMAGe syndrome (1 paper, 2021). IMAGe syndrome is characterized by the association of intrauterine growth retardation, metaphyseal dysplasia (and short limbs), adrenal hypoplasia congenita, and genital anomalies. "However, there are common mutations that repeatedly occur in unrelated patients, the most striking example of which is POLD1 c.1686 + 32C > G in IMAGe syndrome." (PMID 33477564, 2021).
Immunodeficiency (1 paper, 2023). Failure of the immune system to protect the body adequately from infection, due to the absence or insufficiency of some component process or substance. "Pold1 encodes the catalytic subunit of the DNA polymerase delta (PolD) complex, which is involved in the synthesis of the lagging strand during DNA replication and in several DNA damage repair pathways, and its mutation in humans results in immunodeficiency." (PMID 36860866, 2023).
Insulin resistance (1 paper, 2022). Increased resistance towards insulin, that is, diminished effectiveness of insulin in reducing blood glucose levels. "The reported patients presented growth retardation, sensorineural deafness, loss of subcutaneous adipose tissue and insulin resistance, indicating that decreased POLD1 activity exerts organ-specific effects." (PMID 35876795, 2022).
lentivirus infection (1 paper, 2020). Virus diseases caused by the Lentivirus genus. "Stable cell lines overexpressing wild‐type POLD1 or mutant POLD1 (c.56G>A, p.Arg19His) were constructed by lentivirus infection." (PMID 32432416, 2020).
Lymphatic Metastasis (1 paper, 2025). Transfer of a neoplasm from its primary site to lymph nodes or to distant parts of the body by way of the lymphatic system. "Notably, NSD3 and POLD1 were highly mutated in patients with lymphatic metastasis compared to those without lymphatic metastasis." (PMID 39980551, 2025).
malignant peripheral nerve sheath tumor (1 paper, 2024). Malignant peripheral nerve sheath tumor (MPNST) is a rare and often aggressive soft tissue sarcoma occurring in a wide range of anatomical sites. "Of all 15 patients, ten had POLE mutation (one A252V variant was germline), four had POLD1 mutation (one R682Q variant was germline), and one had malignant peripheral nerve sheath tumor with both POLE and POLD1 mutations." (PMID 39218995, 2024).
metastatic prostate carcinoma (1 paper, 2024). A carcinoma that arises from the prostate gland and has spread to other anatomic sites. "Given that ADT is fundamental in treating metastatic prostate cancer, our objective was to identify compounds with the strongest correlation with POLD1 among androgen-related compounds." (PMID 38918844, 2024).
optic nerve glioma (1 paper, 2023). A glioma that affects the optic nerve. "An optic nerve glioma had been diagnosed at under one year of age in the sibling of a POLD1 variant carrier." (PMID 37990341, 2023).
osteosarcoma (1 paper, 2022). A usually aggressive malignant bone-forming mesenchymal neoplasm, predominantly affecting adolescents and young adults. "Intriguingly, siRNA-mediated POLD1 depletion impaired proliferation and/or invasive potential, and increased genome instability of (liver, breast, cervical and osteosarcoma) cancer and normal cells, which confirmed the key role of POLD1 in cell cycle progression and DNA damage repair." (PMID 35189839, 2022).
Pca (1 paper, 2023). "By combining both KEGG analysis and GO term analysis, seven genes (RNASEH2A, RFC2, RFC4, LIG1, POLD1, POLD2, and POLE4) were identified as new biomarker genes upregulated in CRPC compared to localized Pca and associated with DNA replication and DNA repair." (PMID 37950047, 2023). "We identified six DDR-related genes (Ribonuclease H2 Subunit A (RNASEH2A), replication factor C subunit 2 (RFC2), RFC4, DNA Ligase 1 (LIG1), DNA polymerase D1 (POLD1), and DNA polymerase E4 (POLE4)) that were upregulated in CRPC compared with Pca tissues." (PMID 37950047, 2023).
rectum adenocarcinoma (1 paper, 2022). An adenocarcinoma arising from the rectum. "While increased POLD1 expression was significantly associated with decreased TMB in rectum adenocarcinoma (READ)." (PMID 35189839, 2022).
renal medullary carcinoma (1 paper, 2024). "Patient SYSUCC07, diagnosed with R682Q POLD1 germline mutant renal medullary carcinoma, achieved partial response after two doses of toripalimab." (PMID 39218995, 2024).
retinoblastoma (1 paper, 2025). A malignant tumor that originates in the nuclear layer of the retina. "The highest agreement between RNA and protein level was observed for DDB2, CHAF1B, and POLD1, which were upregulated in retinoblastoma, and RHO, PDE6A, and CRABP1, which were downregulated." (PMID 40395327, 2025).
serrated polyposis (1 paper, 2023). "At the same time, the detected POLD1 frameshift variant segregated in three additional family members with serrated polyposis." (PMID 36756361, 2023).
small intestine cancer (1 paper, 2025). A primary or metastatic malignant neoplasm involving the small intestine. "One NTRK fusion-positive CRC patient’s tumor was MSI-H, TMB-H (91.6 mut/Mb) and PD-L1 IHC positive (CPS score = 80%) with a POLD1 co-mutation, and another case with metastatic small intestine cancer was also MSI-H and TMB-H (80 mut/Mb) with a POLD1 co-mutation." (PMID 40385986, 2025).
T-cell immunodeficiency (1 paper, 2022). A broad classification of disorders that affect the cell-mediated aspect of the immune response. "Moreover, the defective POLD1 function caused by its mutation has been regarded as a cause of T cell immunodeficiency." (PMID 35189839, 2022).
Thrombocytopenia (1 paper, 2017). A reduction in the number of circulating thrombocytes. "RPA1 and POLD1 presented consecutive significant signals on thrombocytopenia." (PMID 28924235, 2017).
thymoma (1 paper, 2022). A neoplasm arising from the epithelial cells of the thymus. "While increased POLD1 expression was significantly associated with decreased TMB in thymoma (THYM)." (PMID 35189839, 2022).
triple-negative breast carcinoma (1 paper, 2023). An invasive breast carcinoma which is negative for expression of estrogen receptor (ER), progesterone receptor (PR), and human epidermal growth factor receptor 2 (HER2). "In addition, POLD1 status likely affects the treatment response, especially in triple-negative breast cancer." (PMID 36980791, 2023).
uveal melanoma (1 paper, 2023). A melanoma derived from melanocytes of the uveal tract. "We previously observed intron retention in POLD1 (exon 22–23), PNKP (exon 19–20), ATM, and ATR in uveal melanoma cell lines treated with PRT543 with concomitant loss in protein expression." (PMID 37861290, 2023).
cancer (142 papers, 2013 to 2026). A tumor composed of atypical neoplastic, often pleomorphic cells that invade other tissues. "A large pan-cancer cohort study identified POLE/POLD1 mutations as independent predictors of ICI response across solid tumors, with affected patients demonstrating higher ORR and improved survival." (PMID 41019039, 2025). "POLD1 mutations emerge as dynamic architects of cancer biology, intertwining genomic instability with immune evasion while unveiling novel therapeutic avenues." (PMID 40661943, 2025). "Germline and somatic POLE/POLD1 mutations compromising the polymerase fidelity cause cancers with high mutational burden." (PMID 41263451, 2025). "The impact of POLD1 mutations in cancer is complex, with distinct roles in germline and somatic contexts." (PMID 40661943, 2025). "Somatic POLE/POLD1 mutations occur across many cancer types, but are particularly frequent in colorectal and endometrial cancer and in brain tumours of children with constitutional DNA mismatch repair deficiency (CMMRD)." (PMID 41263451, 2025). "Pan-cancer analyses reveal that patients with POLD1-mutated tumors achieve superior outcomes with ICIs, including prolonged overall survival (34 months for POLD1-mutated vs. 18 months for wild-type MSS tumors) and response rates > 80% in some studies." (PMID 40661943, 2025). "This pattern closely resembled mutation signature SBS20, which is found in human cancers harboring POLD1 mutations." (PMID 41279254, 2025). "Independently from the ClinGen panel, recommendations for the classification of POLE and POLD1 variants in the context of cancer predisposition have also been published." (PMID 40237887, 2025). "Ongoing collaborative efforts will be crucial to refine classification frameworks and provide accurate and clinically relevant interpretation of these variants as our understanding of POLD1-associated cancer predisposition evolves." (PMID 41487566, 2025). "The discovery of a multitude of POLE/POLD1 mutations in human cancers in the 2010s further boosted functional analysis efforts, which now specifically focused on cancer-associated variants with suspected clinical significance." (PMID 41263451, 2025). "In somatic MSS cancers, POLD1 exonuclease domain mutations uniquely mimic MSI-H hypermutation, boosting neoantigen load and distinguishing them from typical MSS tumors." (PMID 40661943, 2025). "The maintenance of microsatellite stability despite high mutational burden represents a unique feature of POLD1-mutated cancers and has significant implications for their biological behavior and therapeutic responsiveness." (PMID 40661943, 2025). "Molecularly, the apparent contradiction between functional studies suggesting near-haplosufficiency and the dominant inheritance pattern of POLD1-related cancer predisposition (like PPAP) warrants clarification." (PMID 40661943, 2025). "Integrating structural insights, molecular mechanisms, and clinical data, this review positions POLD1 mutations as both a driver of cancer progression and a promising biomarker, redefining therapeutic possibilities in precision oncology." (PMID 40661943, 2025). "PolED also helps interpret germline POLE and POLD1 variants to facilitate risk assessment and surveillance of families with cancer predisposition syndromes." (PMID 41263451, 2025). "Overall, we found that the heterozygous POLD1 L474P increases the mutation rate by less than 15% in both soma and germline, while in the associated cancers, somatic loss of the wildtype copy of POLD1 leads to a dramatic increase in mutation rate." (PMID 38658779, 2024). "An analysis of a database of 47721 patients with different types of cancer found that patients with POLE/POLD1 mutations nearly doubled their OS after immunotherapy as compared with those with wild-type disease." (PMID 39530091, 2024). "Cancers often develop in individuals with constitutional MMRD as a result of early somatic-driver mutations in POLE or POLD1." (PMID 39204096, 2024).
cancer (continued). "Meanwhile, somatic inactivation of the second copy of POLD1 on the background of a heterozygous constitutional POLD1 exonuclease mutation is under strong positive selection and is likely a major avenue for cancer development." (PMID 38658779, 2024). "Even though POLD1-mutated cancers are believed to be primarily microsatellite stable, some ECs and CRCs possess microsatellite instability (MSI)." (PMID 36980791, 2023). "A recent study that analysed mutations in POLD and POLE from the cancer patient cohort in cBioPortal observed high levels of POLE/POLD1 mutations in several cancer types, including in 185 out of 2586 (7.2%) esophagogastric cancer samples." (PMID 37568604, 2023). "The genetic mutations and expression profiles in POLD1-mutated cancers have recently gained remarkable attention." (PMID 36980791, 2023). "Nevertheless, apart from malignancies mentioned in the previous paragraphs, several different cancers have been reported to harbor POLD1 mutation as well." (PMID 36980791, 2023). "In recent years, POLD1 germline and somatic mutations, as well as gene-expression patterns, have been extensively studied in cancers." (PMID 36980791, 2023). "The proofreading defect caused by inactivating mutations in the POLD1 proofreading (exonuclease) domain leads to a significant increase in somatic mutation load and cancer risk." (PMID 37047824, 2023). "First, we offered multiprong evidence to support the reclassification of this mutation class to likely pathogenic, and linked the POLD1 DEDD motif mutation to human cancers." (PMID 38067377, 2023). "Meanwhile, recent studies have also indicated that the POLD1 proofreading domain mutation can potentially predict the clinical benefit in cancer patients that are treated with immune-checkpoint inhibitors (ICIs)." (PMID 37047824, 2023). "Previous studies investigating the association of POLE/POLD1 mutation with MSI status in various cancers have shown ambiguous results." (PMID 36980791, 2023). "Both germline and somatic alterations in the proofreading domain of POLD1 have been implicated in various diseases, including cancers." (PMID 36980791, 2023). "Since the first description in 2013 of a correlation between the POLD1 mutation and dominantly inherited intestinal adenomas and carcinomas, two terms regarding this phenomenon have been coined." (PMID 36980791, 2023). "Identifying the POLD1 gene mutation can be important for genetic counseling and clinical surveillance in different clinical avenues including hearing, cardiovascular, and cancer predisposition." (PMID 35356184, 2022). "Patients with POLE/POLD1 mutations harbored a markedly favorable prognosis in a pan‐cancer ICI cohort contained 1644 patients." (PMID 34862763, 2022). "POLE/POLD1 mutation is not only closely related to tumor formation, but also a potential molecular marker for predicting the efficacy of immunotherapy in pan-cancer species." (PMID 35780178, 2022). "As the mutation in POLD1 gene is associated with the development of multiple types of cancers, scrutinizing the deleterious nonsynonymous SNPs of this gene is crucial." (PMID 35620275, 2022). "Recent studies demonstrated that POLD1 proofreading domain mutation can potentially predict desirable outcomes in cancer patients treated with immune-checkpoint inhibitors (ICIs)." (PMID 35189839, 2022). "A defective DNA proofreading function caused by POLD1 mutation contributes to carcinogenesis, while POLD1 overexpression predicts poor prognosis in cancers." (PMID 35189839, 2022). "Cancers with POLE exonuclease domain mutations show very high single-base substitution (SBS) mutation burdens whereas those with POLD1 exonuclease domain mutations show less elevated SBS burdens but are often associated with microsatellite instability." (PMID 34594041, 2021). "Another source of hypermutation in cancer is defective DNA polymerase proofreading due to mutations in polymerase ε (POLE) or polymerase δ (POLD1) genes." (PMID 33879792, 2021).